SIRT1 (sirtuin 1)
Diseases named in the same sentence as SIRT1 in open-access papers (continued):
Sharing a sentence is not in itself a finding about the gene and the disease.
Insulin resistance (continued). "SIRT1/AMPK signaling is an energy-sensitive pathway that regulates various physiological reactions, including catabolic metabolism, angiogenesis, cell survival, and insulin resistance, and can antagonize the pathogenesis of NAFLD." (PMID 34681600, 2021). "The data described in this review reveal SIRT1 and SIRT6 as multifaceted mediators of energy metabolism, affecting processes such as food intake, food preference, puberty, body weight, adiposity, glucose homeostasis and insulin resistance." (PMID 33572672, 2021). "Meanwhile, hyperandrogenism led to the negative regulation of BMAL1-induced expression of NAMPT/NAD+/SIRT1 pathway, further inhibiting downstream GLUT4 and contributing to insulin resistance in mature adipose cells, which was consistent with our previous results in HepG2 cells." (PMID 32334629, 2020). "Based on the arrhythmic Nampt and Sirt1 mRNA expressions in the liver and adipose of PCOS-like rats, we speculated that NAMPT and SIRT1 might be the bridge linking BMAL1 and insulin resistance in PCOS patients." (PMID 32334629, 2020). "Vitamin D (VD) may increase sirtuin 1 (SIRT1) and subsequently PPAR-γ coactivator 1α (PGC-1α) and irisin levels and these improvements may reduce insulin resistance (IR)." (PMID 32033527, 2020). "MNAM activates SIRT1 and inhibits acetylation of FOXO1, which in turn regulates insulin sensitivity in type 2 diabetic mice, leading to a reduction of hepatic glucose output and improvement of insulin resistance." (PMID 32280711, 2020). "However, further investigation into the targets and functions of SIRT1, SIRT2, SIRT3, and SIRT6 will aid in the development of new strategies to treat insulin resistance and T2DM." (PMID 30972029, 2019). "The SIRT1 activation by RES improves palmitate-induced inflammation and insulin resistance, ameliorates the HG-induced impairment of HUVECs, induces mitochondrial biogenesis in aortic endothelial cells of db/db mice, and improves aortic dysfunction in diabetic mice." (PMID 31068817, 2019). "Adiponectin activates AMPK by binding to adipoR1, thereby activating SIRT1, and deacetylating PGC-1α improves oxidative stress, mitochondrial function, glucose/lipid metabolism, and exercise endurance, resulting in improved insulin resistance and T2DM." (PMID 30972029, 2019). "SIRT1 is a Nicotinamide Adenine Dinucleotide (NAD)+-dependent protein deacetylase, and it is involved in the deacetylation of the nuclear receptors, playing a critical role in insulin resistance development." (PMID 31572434, 2019). "In conclusion, MF and GLP-1 receptor agonists, such as EX, can significantly improve insulin resistance in PCOS rats, and their action may be in relation to the AMPKα-SIRT1 pathway." (PMID 31526389, 2019). "The regulation of SIRT1 by strigolactone GR24 and the activation of AMPK by pinosylvin may offer novel therapeutic approaches in the treatment of insulin resistance in skeletal muscle." (PMID 29242624, 2017). "In particular, a SIRT1 inhibitor EX527 significantly prevented BCH-induced increased phosphorylation of insulin signaling molecules, suggesting that SIRT1 activation was involved in BCH-induced improvement in insulin resistance in HF/HFr-fed mouse hepatocytes." (PMID 27874078, 2016). "SIRT1) and non-genomic pathways (i.e., ER signalling), which will in turn improve cognitive function, but will also counteract insulin resistance in T2DM, as previously discussed in our first report of this study." (PMID 27420093, 2016). "The current study provides evidence that increasing SIRT1 expression has no obvious impact on the development of glucose-induced insulin resistance in skeletal muscle." (PMID 25798922, 2015). "SIRT1 and AMPK, two important nutrient sensors, have been reported to exert multiple protective effects on vascular functions through the inhibition of inflammation, oxidant stress, vascular smooth muscle cell proliferation, and insulin resistance." (PMID 23825667, 2013).
Insulin resistance (continued). "Collectively, these findings indicate that therapy targeting SIRT1/PGC-1α and mitochondria may serve as a novel approach for curbing insulin resistance." (PMID 20981161, 2011). "Mice lacking sirtuin 1 develop adipose tissue hypertrophy, fatty liver, and insulin resistance." (PMID 39917613, 2025). "Moreover, a negative correlation was observed between microRNA-181a and Sirtuin 1 expression, while a positive correlation was noted between microRNA-181a and insulin resistance." (PMID 41155523, 2025). "A study also points to TRF’s ability to improve insulin resistance in a diabetic animal model via the insulin receptor substrate 1 (IRS-1) and AMP-activated protein kinase/ Sirtuin 1/ Peroxisome proliferator-activated receptor-γ coactivator 1-α (AMPK/SIRT1/PGC1α) pathways." (PMID 38916919, 2025). "Moreover, a negative correlation between miRNA-181a and SIRT1 expression was observed, while a correlation between miRNA-181a and insulin resistance was positive." (PMID 39768567, 2024). "Notably, the activation of AMPK by berberine may be dependent on SIRT1, as SIRT1-knockdown cells blocked AMPK activation and prevented the effect of berberine on diet-induced insulin resistance." (PMID 38976215, 2024). "Furthermore, our research discovered that individuals with insulin resistance and metabolic syndrome have notably lower levels of SIRT1 gene expression compared to those who do not have these conditions." (PMID 37862340, 2023). "In addition, the current research level is relatively superficial, and it is only speculative based on the experimental results of existing studies, such as the clear treatment mechanism of SIRT1 and AMPK pathways in insulin resistance." (PMID 36030228, 2022). "Although Sirt1 and Sirt3 activation able to reduce insulin resistance, we could not observe any additional benefit with the combination." (PMID 33668369, 2021). "SIRT1 functions, in whole or in part, by activating AMPK via inducing deacetylation of LKB1 under adverse situations that may lead to intracellular stress, including hypoxia, insulin resistance, and oxidative stress." (PMID 34356308, 2021). "In contrast, the overexpression of Sirt1 in skeletal muscle in vivo does not improve insulin resistance and had little impact on mitochondrial metabolism, suggesting that the overexpression of Sirt1 protein is not the single factor involved in insulin sensitization of skeletal muscle." (PMID 32796716, 2020). "BBR and SIRT1 show striking similarities in the regulation of insulin sensitivity involving the AMPK pathway and inflammatory response in adipose tissue, suggesting that BBR may depend on the Sirt1 pathway to improve insulin resistance." (PMID 33390968, 2020). "Thus, SIRT1-induced PGC-1α deacetylation leads to the improvement of mitochondrial function via mitochondrial biogenesis and induction of GLUT4 and adiponectin, demonstrating the beneficial effects against insulin resistance and T2DM." (PMID 30972029, 2019). "One may hypothesize that lack of response of AT SIRT1 to insulin represents an early metabolic abnormality in this group, even before the onset of overt insulin resistance, measured as a decreased insulin-stimulated glucose uptake." (PMID 29417372, 2018). "Therefore we conclude that acute increases in SIRT1 protein have little impact on mitochondrial content and that overexpressing SIRT1 does not prevent the development of insulin resistance during hyperglycaemia." (PMID 25798922, 2015). "In conclusion, our results suggest that although a decrease in SIRT1 may be involved in the development of insulin resistance in skeletal muscle in response to hyperglycaemia, overexpressing SIRT1 does not alleviate this insulin resistance." (PMID 25798922, 2015). "Moreover, our previous study demonstrated that insulin resistance could reduce cellular NAD+ levels and SIRT1 activity in vivo." (PMID 26110043, 2015).
Insulin resistance (continued). "Thus, we propose that insulin resistance may regulate DNMT1 activity and DNA methylation in the D-loop region through NAD+-SIRT1, and this mechanism should be further explored in future studies." (PMID 26110043, 2015). "However, PGC-1α and SIRT1 proteins exhibited a declining trend, suggesting that the heart relies on glycolipid metabolism rather than mitochondrial biosynthesis for energy during insulin resistance." (PMID 39761309, 2025). "Thus, while SIRT1 and SIRT6 positively regulate glucose uptake and fatty acid oxidation in skeletal muscle, SIRT1 activity is inhibited by SIRT4 and balanced by SIRT3, which inhibits fatty acid oxidation and affects ROS production, thereby influencing insulin resistance." (PMID 37006625, 2023). "However, other studies showed that upregulation of SIRT1 in skeletal muscle cells does not increase the total energy expenditure or enhance insulin sensitivity in mice fed a normal diet or HFD, nor does SIRT1 overexpression alters glucose-induced insulin resistance in rats." (PMID 33806509, 2021). "However, the alleviating effects of BBR on insulin resistance and inflammation in obese mice were not completely eliminated by SIRT1 knockout, which may be because the present study used SIRT1 heterozygous knockout mice." (PMID 33390968, 2020). "Additionally, Sirt-1 also plays a significant role in the glucose and fat homeostasis by regulating various transcription factors; reduction in Sirt-1 activity due to either HFD or unhealthy diet leads to insulin resistance, altered immunity, mitochondrial apoptosis, and NAFLD." (PMID 33384592, 2020). "Moreover, these mice lacking hepatic Sirt1 exhibit elevated gluconeogenesis, leading to hyperglycemia and insulin resistance, which suggests that hepatic SIRT1 plays a role in not only protecting the liver from steatosis, but also in maintaining whole-body glucose metabolism." (PMID 33193730, 2020). "Overexpression and activation of SIRT1 protect against high fat diet- (HFD-) induced metabolic abnormalities in mice, such as insulin resistance, glucose intolerance, and liver steatosis, without extending their lifespan." (PMID 25400942, 2014). "Both of them concluded that mild overexpression of SIRT1 (2- to 4-fold higher, depending on the tissue) prevented HFD-induced glucose intolerance, insulin resistance and hepatic steatosis, despite no significant alteration in body weight." (PMID 24567900, 2014). "We reasoned that if quenching inflammation is required for the full strength of AICAR to prevent insulin resistance, AICAR will not be effective in prevention of insulin resistance in MSKO mice, since AICAR likely fails to suppress the enhanced inflammation due to the absence of SIRT1." (PMID 23183898, 2012).
Hepatic steatosis (337 papers, 2008 to 2026). Steatosis is a term used to denote lipid accumulation within hepatocytes. "CVS-induced suppression of SIRT1, previously associated with hepatic steatosis and inflammation, was dose-dependently reversed by NR." (PMID 41566055, 2026). "In NAFLD patients, hepatic SIRT1 mRNA levels are downregulated and negatively associated with hepatic steatosis and fibrosis." (PMID 40427561, 2025). "New data suggest that a reduction in the SIRT1 activity increases the risk of fatty liver in response to dietary fat." (PMID 40766326, 2025). "In particular, miR132 targets such as phosphatase and tensin homolog (Pten), Forkhead box O3 (FOXO3), and sirtuin 1 (Sirt1) are associated with hepatic steatosis, hyperlipidemia, and glucose regulation." (PMID 39596297, 2024). "Using DIO mice, we demonstrated that, in response to overloaded lipid stress, the level of hepatic CARF decreased along with the downregulation of Sirt1, pAMPK, and pACC, which are causal factors for hepatic steatosis." (PMID 37048142, 2023). "In methionine- and choline-deficient (MCD) diet-fed mice, SUV39H2 promoted hepatic steatosis by downregulating SIRT1, a NAD+-dependent histone deacetylase executing a protective role in the liver (more details in Section 2.4)." (PMID 37834101, 2023). "Several mechanisms of SIRT-1 are beneficial to alleviate these disorders, including the decreased risk of liver steatosis in response to a high-fat diet via modifying lipogenesis and liver fat export." (PMID 36991247, 2023). "In the hyperlipidemia-induced hepatic steatosis and atherosclerotic mice, SIRT1 restores cholesterol efflux caused by hyperlipidemia through regulating the LXRα/β-PPARγ pathway." (PMID 36632457, 2023). "Some studies have reported that liver-specific disruption of SIRT1 not only causes hepatic steatosis but also promotes the progression to an advanced metabolic disorder stage such as lipotoxicity." (PMID 35740337, 2022). "Our previous study found that SIRT1 is a key factor in mediating the weight loss response and reducing hepatic steatosis by GLP-1RA." (PMID 35624499, 2022). "We also demonstrated the role of Grail in hepatic steatosis and the molecular mechanisms underlying targeted degradation of Grail-bound Sirt1." (PMID 33771967, 2021). "Sirt1 liver-specific knockout causes hepatic steatosis and promotes the progression to advanced metabolic disorders." (PMID 34575829, 2021). "Previous studies have also shown that SIRT1 heterozygous deficient mice exhibited exacerbated HFD-induced hepatic steatosis and inflammation as well as insulin resistance." (PMID 34483906, 2021). "In the liver, the SIRT1-mediated activation of FGF21 prevented liver steatosis caused by fasting, indicating the possible relationship between sirtuins and FGF21." (PMID 34368135, 2021). "In contrast, SIRT1 is involved in the pathogenesis of the inflammation-associated fatty liver disease." (PMID 34483906, 2021). "The present study indicates that low SIRT1 expression caused by hepatic steatosis promotes hepatic fatty acid synthesis and inhibits fatty acid β-oxidation." (PMID 32230804, 2020). "Concomitant with the occurrence of hepatic steatosis, oxidative stress is an established risk factor for the development of lipid metabolism disorders at least partly through the SIRT1-SREBP-1c/ PGC-1α signaling pathway." (PMID 32230804, 2020). "This study explores the effect of hepatic steatosis on the expression of the SIRT1 gene and protein and the proteins encoded by the genes downstream to it, all of which are involved in lipid metabolism in the liver." (PMID 32230804, 2020). "A significantly lower level of SIRT1 was found in obese associated liver steatosis compared to normal patients." (PMID 32365537, 2020). "Conversely, hepatocyte-specific knockout of SIRT1 can cause significant hepatic steatosis and aggravate liver inflammatory responses." (PMID 30995792, 2019).
Hepatic steatosis (continued). "While SIRT-1 over-expression or activation promotes lipolysis, fat loss and remarkably protects high-fat diet induced obese mice from liver steatosis." (PMID 29563875, 2018). "Liver-specific knockout mice develop hepatic steatosis and inflammation under HFD, while global transgenic mice overexpressing Sirt1 were protected against hepatic steatosis caused by HFD." (PMID 28207798, 2017). "Sirtuin 1 is a longevity gene and regulates lipid homeostasis, while lipid homeostasis the critical reasons in the development of fatty liver caused by alcohol." (PMID 28360860, 2017). "In this study, we found that PPARγ is activated in alcohol-induced hepatic steatosis and associated with reducing SIRT1 activity upon ethanol metabolism." (PMID 27404390, 2016). "Hepatic deletion of SIRT1 impaired peroxisome proliferator-activated receptor α function, decreased fatty acid beta-oxidation and caused hepatic steatosis." (PMID 26232096, 2015). "Metformin treatment also activated AMPK and SIRT1 in the liver, which was also associated with the amelioration of the hepatic steatosis observed in the HED group." (PMID 25895126, 2015). "Overexpression of SIRT1 reduced body weight gain and prevented hepatic steatosis associated with a high-fat diet." (PMID 24009212, 2013). "Chronic HFD causes an accumulation of lipids in the liver leading to fatty liver disease and SIRT1 was recently shown as a potential therapeutic target for treatment fatty liver disease." (PMID 22761194, 2012). "Sirt1 is a well-studied nuclear sirtuin with beneficial metabolic effects, and it has been implicated in the improvement of hepatic steatosis." (PMID 21373642, 2011). "This relationship prompted us to further investigate whether the PPARα/SIRT1-AMPK pathway was involved in miR-34a-regulated hepatic steatosis and its associated pathology." (PMID 41223206, 2025). "The TNF induced DBC1 and SIRT1 pathway may be an important pharmacological target to improve metabolic disorders, such as type 2 diabetes, fatty liver disease, and diseases with known associations between inflammation and metabolism." (PMID 40766326, 2025). "In addition, SIRT1 activation can contribute to the improvement of fatty liver by reducing the increase in VLDLR levels caused by ER stress during MASLD." (PMID 38807218, 2024). "Inhibition of SIRT1 by Ex527 also caused a decrease in the ATP content, relative mtDNA level, and mitochondrial complex activity and increased lipid oxidation, abolishing the E2 benefits preventing hepatic steatosis." (PMID 38136219, 2023). "Parallel to this, SIRT1 suppression in the mouse liver is sufficient to cause hepatic steatosis, an effect that may be mediated via Ppar-γ and Pparα, the key regulators of glycolysis and lipolysis." (PMID 37190114, 2023). "Lycopene can also modulate hepatic lipid metabolism and avoid the hepatic steatosis caused by a high-fat diet by activating SIRT1 and consequently suppressing lipogenesis, promoting lipid catabolism in the liver and skeletal muscles, and mobilizing lipids in white adipose tissue." (PMID 35883529, 2022). "MiR-34a is also upregulated in serum samples of NAFLD/NASH patients, and miR-34a downregulates the expression of several key genes in NAFLD pathogenesis, including HNF4α, PPARA, and SIRT1 expressions, which are associated with higher triglycerides accumulation and liver steatosis." (PMID 36612019, 2022). "Therefore, this study aimed to investigate the role of SIRT1 in the metformin-improved fatty liver and the underlying mechanisms." (PMID 34483906, 2021). "However, the underlying molecular mechanisms, the effect of hepatic steatosis on the expression of SIRT1 genes and proteins and the expressions and activities of downstream lipid-metabolism-related proteins and key enzymes, have not yet been fully clarified." (PMID 32230804, 2020).